TAC4 (tachykinin precursor 4)
Description:
Tachykinins are active peptides which excite neurons, evoke behavioral responses, are potent vasodilators and secretagogues, and contract (directly or indirectly) many smooth muscles. Endokinin-A induces thermal hyperalgesia and pain-related behavior such as scratching following intrathecal administration in rats. These effects are suppressed by treatment with endokinin-C. Endokinin-A/B reduces arterial blood pressure and increases sperm motility.
Synonyms: PPT-C; HK-1; Pptc; EK
Tractability: Antibody: UniProt places it where antibodies can reach, with high confidence; UniProt predicts a signal peptide or a membrane-spanning region; its Gene Ontology location is reachable by antibodies, with medium confidence.
Gene: Protein-coding gene on chromosome 17 (49,838,300 to 49,848,069, reverse strand). Ensembl gene ENSG00000176358.
Subcellular location: Secreted
Gene Ontology:
Molecular function: substance P receptor binding
Biological process: positive regulation of flagellated sperm motility; inflammatory response; positive regulation of cytosolic calcium ion concentration; tachykinin receptor signaling pathway
Cellular component: extracellular region
Genetic constraint (gnomAD): Loss-of-function variants: 17 observed, 18.16 expected, observed/expected ratio (o/e) 0.94, 90% interval 0.64 to 1.4. The upper end of that interval is the gene's LOEUF score, 1.4, which puts it in group 5 of 6, group 1 being the genes least tolerant of losing a copy. Missense variants: 118 observed, 128.9 expected, observed/expected ratio (o/e) 0.92, 90% interval 0.79 to 1.07. Synonymous variants: 62 observed, 53.98 expected, observed/expected ratio (o/e) 1.15, 90% interval 0.94 to 1.42.
Homologues: Orthologues: chimpanzee TAC4 (96% identical), pig TAC4 (61% identical), rabbit TAC4 (59% identical), dog TAC4 (58% identical), guinea pig Tac4 (49% identical), mouse Tac4 (49% identical), rat Tac4 (38% identical).
Diseases named in the same sentence as TAC4 in open-access papers:
TAC4 is named in the same sentence as 18 diseases in open-access papers, as found by Europe PMC text mining. Sharing a sentence is not in itself a finding about the gene and the disease. The quoted sentences say what the papers report.
COVID-19 (4 papers, 2021 to 2023). A disease caused by infection with severe acute respiratory syndrome coronavirus 2. "In addition, recent genome-wide association studies (GWAS) have identified several SNPs, including the BCL11A (rs1123573) and TAC4 (rs77534576) genes, that are associated with COVID-19 severity." (PMID 37112884, 2023). "A summary data-based Mendelian randomization (SMR) analysis and a transcriptome-wide association study (TWAS) were performed for the severe COVID-19 dataset, and seven novel genes for severe COVID-19 were identified, including CCR5, CCR5AS, IL10RB, TAC4, RMI1, and TNFSF15." (PMID 36483456, 2022).
osteosarcoma (3 papers, 2023). A usually aggressive malignant bone-forming mesenchymal neoplasm, predominantly affecting adolescents and young adults. "The overall expression of TAC4 was low and mainly expressed in chondroblastic osteosarcoma cells." (PMID 37055822, 2023). "Although there were no available antibodies to TAC4, the protein expression of MYC, P4HA1, and RAMP1 was found to be significantly higher in osteosarcoma tissues than in normal tissues." (PMID 37055822, 2023).
Arthritis (2 papers, 2013 to 2020). Inflammation of a joint. "In inflammatory pain and arthritis, a pro-inflammatory component is also likely to contribute to its action, since HK-1 expression was described in the immune system as well and Tac4 deficiency also alleviated experimental lung inflammation." (PMID 32331300, 2020). "The semiquantitative scoring obtained from measuring the characteristic inflammatory parameters demonstrates the significantly decreased severity of arthritis in Tac4−/− and Tac1−/−/Tac4−/− mice." (PMID 23626716, 2013). "Although the patterns and levels of expression of Tac1- and Tac4-derived peptides at early time points prior to the immune response initiation is not known, the present results outline the complexity of the tachykinin system in different mechanisms in arthritis and arthritis-related pain." (PMID 23626716, 2013).
acute lymphoblastic leukemia (1 paper, 2012). Leukemia with an acute onset, characterized by the presence of lymphoblasts in the bone marrow and the peripheral blood. "The expression of TAC4 mRNA in human B lymphocytes is upregulated in chronic lymphocytic leukemia and non-Hodgkin's lymphoma, but downregulated in acute lymphoblastic leukemia." (PMID 22384199, 2012).
Anxiety (1 paper, 2020). Intense feelings of nervousness, tension, or panic often arise in response to interpersonal stresses. "This is supported by the observations that the phenotype of Tac4-/- deficient mice in chronic pain models is different from SP or NK-1 receptor-deficient mice and an opposite phenotype was also described in models of anxiety and depression as well." (PMID 32331300, 2020).
glioma (1 paper, 2023). A benign or malignant brain and spinal cord tumor that arises from glial cells (astrocytes, oligodendrocytes, ependymal cells). "Previous study has shown that TAC4 mRNA expression in gliomas, indicating a possible involvement of HK-1 in glioma biology." (PMID 36807122, 2023).
migraine (1 paper, 2022). "Neuropeptides directly associated with pain or migraine from significantly differentially expressed neuropeptide prohormone genes include apelin (APLN), cortistatin (CORT), IGF2, neuromedin B (NMB), neuropeptide W (NPW), PDGFA and platelet-derived growth factor, D polypeptide (PDGFD), TAC4, and VIP." (PMID 35453627, 2022).
cancer (1 paper, 2019). A tumor composed of atypical neoplastic, often pleomorphic cells that invade other tissues. "However, the remaining eight cancer-specific DESPGs of GLB1, HSPA5, PDIA3, GNRH1, IFNGR2 ADAM9, TPST2, and TAC4) were not reported in any researches, which could be potential novel prognostic biomarkers in corresponding tumors." (PMID 31824949, 2019).
TAC4 also shares sentences with these, for which no sentence is quoted: tumor (2 papers); Allergy (1); Arrhythmia (1); chronic lymphocytic leukemia (1); depression (1); endometrial carcinoma (1); Kidney (1); non-Hodgkin lymphoma (1); respiratory failure (1); Thyroid carcinoma (1).